PROS1 (protein S)
Diseases named in the same sentence as PROS1 in open-access papers (continued):
Sharing a sentence is not in itself a finding about the gene and the disease.
thrombophilia (continued). "Additional thrombophilia workup of functional assays for antithrombin III, protein S deficiency, polymerase chain reaction for factor V Leiden mutation, and testing for antiphospholipid antibodies and homocysteine levels revealed reduced protein S function and protein C at borderline." (PMID 40084314, 2025). "Thrombophilia is a major predisposing risk factor for BCS, encompassing both inherited causes such as protein C, protein S, antithrombin III deficiency, Factor V Leiden mutation, and acquired conditions including antiphospholipid syndrome, hypercoagulable states, and myeloproliferative disorder." (PMID 41394931, 2025). "In most reported pheochromocytoma cases with thrombosis, intrinsic thrombophilia (inherited protein S deficiency, factor V Leiden, etc.)was not identified, suggesting the low protein S activity is usually acquired and reversible." (PMID 41357012, 2025). "Inherited thrombophilia, characterized by a genetic predisposition to venous thromboembolism (VTE), includes deficiencies of natural anticoagulants such as protein S, protein C, and antithrombin, as well as gain-of-function mutations like Factor V Leiden and the prothrombin G20210A variant." (PMID 40981007, 2025). "This systematic review and meta-analysis assesses venous thromboembolism (VTE) risk in adults with hereditary thrombophilia, including Factor V Leiden (FVL) mutation, prothrombin G20210A (FII) mutation, compound heterozygosity, protein C (PC), protein S (PS), and antithrombin (AT) deficiency." (PMID 39167180, 2024). "The cleavage of PROS1 by PLpro may disrupt its anticoagulant and immunomodulatory functions, potentially contributing to the hypercoagulable state observed in COVID-19 patients." (PMID 38398746, 2024). "Additionally, mutations that cause deficiencies in natural anticoagulants, such as ATIII, protein C, and protein S, can also lead to thrombophilia." (PMID 39534247, 2024). "A suspicion of inherited thrombophilia was raised, and genetic testing confirmed it, with a positive PAI-1 4G/5G promoter homozygous gene mutation, MTHFR C677T heterozygous gene mutation, and Protein S and Protein C deficiencies." (PMID 37510971, 2023). "A small group of our subjects (9.9%) had thrombophilia, including the presence of anticardiolipin antibody (ACA) IgG; confirmed antiphospholipid syndrome (APS); sticky platelet syndrome (SPS); deficiencies of protein C/protein S or antithrombin III." (PMID 37020240, 2023). "Gene sequencing revealed that the proband had a homozygous c.1411T>C (p.Y471H) mutation of PLAT, without common severe thrombophilias such as protein C, protein S, or antithrombin deficiency." (PMID 37808270, 2023). "Protein S deficiency is a form of thrombophilia in which the anticoagulant protein S is underproduced or not produced at all by the body." (PMID 37303358, 2023). "Genetic testing confirmed inherited thrombophilia, positive Factor V Leiden, MTHFR A1298C and MTHFR C677T heterozygous gene mutations, PAI-1 4G/5G promoter homozygous gene mutation, and Antithrombin, Protein S, and Protein C deficiencies." (PMID 37510971, 2023). "Due to various underlying medical conditions (such as acute thrombosis, pregnancy, inflammation, etc.)thrombophilia testing may yield falsely low levels of protein C, protein S and antithrombin as a consequence of the consumption of these factors." (PMID 36013523, 2022). "In addition to hemolysis, acquired hypercoagulability induced several hemostatic changes like TF and phospholipid overexpression, endothelial dysfunction and anticoagulant pathways, with decreased protein S and protein C." (PMID 36277754, 2022). "Our study reviewed different clotting (such as prothrombin time, thrombin time) and thrombophilia (such as protein C activity, antithrombin activity, free protein S) tests before and after DOAC-StopTM and DOAC Filter® treatments in a limited sample of four patients who were not on DOAC treatment." (PMID 36292209, 2022).
thrombophilia (continued). "Protein S deficiency, protein C deficiency, antithrombin deficiency, antiphospholipid syndrome, factor V Leiden (FVL), and hereditary thrombophilia are the types of thrombophilia." (PMID 36865660, 2022). "Inherited thrombophilia (e.g., venous thromboembolism, VTE) is due to rare loss-of-function mutations in anticoagulant factors genes (i.e., SERPINC1, PROC, PROS1), common gain-of-function mutations in procoagulant factors genes (i.e., F5, F2), and acquired risk conditions." (PMID 34207366, 2021). "Extensive tests for thrombophilia (Factor V R5066 (Leiden) mutation, prothrombin mutation, antiphospholipid antibodies, antinuclear antibodies, protein C activity, protein S activity) were negative or inconspicuous." (PMID 33918932, 2021). "This was in line with a study in the Saudi population, in which protein S deficiency was the most dominant form of thrombophilia (14.5%), whereas prothrombin gene mutations and FVL mutations were the least common cause for thrombophilia (in 1.1% and 0.5% of patients, respectively)." (PMID 32351991, 2020). "Although results are controversial, usual standard inherited thrombophilia RM/RIF study includes Factor V Leiden deficiency, activated protein C resistance, prothrombin G20210A and protein S deficiency and, sometimes methylenetetrahydrofolate reductase mutations." (PMID 31058051, 2019). "This phenomenon is created by various mechanisms, including higher production of fibrinogens and coagulation factors, thrombocytosis, increased platelet adhesion, increased urinary excretion of antithrombin III, protein C, protein S, dehydration, diuretic use and inherited thrombophilia." (PMID 27375752, 2016). "Mechanisms for the observed hypercoagulability in HIV infected patients are multifactorial and include the presence of antiphospholipid antibodies and deficiency of natural anticoagulants such as protein C, protein S, heparin cofactor II, and antithrombin." (PMID 24570775, 2013). "Eighty-five Indian patients (age < 45 years) presenting ischemic stroke (n = 48) or myocardial infarction (n = 37) and 50 controls were studied for seven thrombophilia markers including antithrombin (AT), factor V, protein C, protein S, activated protein C resistance (APC-R), fibrinogen and Lp(a)." (PMID 24346777, 2013). "The presence of an inherited thrombophilia should not alter the intensity of anticoagulant therapy, given that antithrombin, protein C, or protein S deficiency, factor V Leiden, and the prothrombin G20210A mutation are not unusually anticoagulant resistant." (PMID 16968541, 2006). "In a UK based family study with 28 index patients with protein S deficiency, first degree relatives with the PROS1 gene defect had a five-fold higher risk of thrombosis than those with a normal gene and no other apparent thrombophilia." (PMID 16968541, 2006). "There exist no data on inherited or acquired thrombophilia such as anticardiolipin antibodies, antithrombin, protein C or protein S deficiency or the prothrombin gene or factor V Leiden mutation in patients with malignant lymphoma." (PMID 15798767, 2005). "A thrombophilia workup was reported in 59 patients, revealing only five positive cases (homozygous MTHFR gene and heterozygous Factor V Leiden mutations, Protein C and S deficiency, HIT and LA hypercoagulability mutation, Inherited Protein S deficiency, and heterozygous PT20210Z gene mutation)." (PMID 40565811, 2025). "Additional thrombophilia workup of functional assays for antithrombin III, protein S deficiency, polymerase chain reaction (PCR) for factor V Leiden mutation, and testing for antiphospholipid antibodies and homocysteine levels revealed elevated antiphospholipid IgM antibody and deficient protein S." (PMID 40018474, 2025).
thrombophilia (continued). "Additionally, thrombophilia testing is advised for asymptomatic individuals with a family history of VTE and known antithrombin, protein C, or protein S deficiency, with the recommendation for thromboprophylaxis in risk situations and avoidance of COC in thrombophilic patients." (PMID 38596262, 2024). "Her outpatient hypercoagulability workup six weeks after hospitalization revealed the following findings: protein S Ag, total - 50% (reference range: 60-150%); protein S Ag, free - 45% (reference range: 61-136%); protein S activity - 14% (reference range: 63-140%)." (PMID 39268299, 2024). "A systematic review and meta-analysis indicated that pregnant women with hereditary thrombophilia had an increased risk of RPL, especially in the presence of G1691A mutation of the factor V Leiden (FVL) gene, the G20210A mutation of the prothrombin gene (PGM), and deficiency of protein S (PS)." (PMID 36902692, 2023). "To rule out thrombophilia, we planned to perform thrombophilia-related examinations, including factor V Leiden, prothrombin 20210A mutation, protein C, protein S, and antiphospholipid antibody, but the patient declined the investigations due to financial constraints." (PMID 36266638, 2022). "The impact of direct oral anticoagulants (DOACs) on laboratory assays used for thrombophilia testing (e.g., antithrombin, protein S, protein C, lupus anticoagulant and activated protein-C resistance) is a well-known issue and may cause false-positive and -negative results." (PMID 31249943, 2018). "This article will discuss the potential arguments for testing of inherited thrombophilia, including factor V Leiden mutation (FVL), prothrombin mutation (FIIm), and deficiencies of antithrombin, protein C, or protein S and suggests some pediatric patient groups, which may be candidates for testing." (PMID 28352625, 2017). "Although the acute thrombosis lowers the levels of protein C, protein S, and antithrombin as well as the initiation of Warfarin lowers the levels of protein C and protein S, normal values rule out those factors as risk factors for hypercoagulability in this patient." (PMID 24073002, 2013). "Positivity rates for the antithrombin, protein C and protein S assays were much higher than would be expected relative to the observed prevalence of FVL and prothrombin G20210A mutations, as well as previously published data on the relative frequencies of inherited thrombophilia defects." (PMID 18384680, 2008). "Furthermore, because RPL was associated to reduced clotting inhibitors also protein C, protein S and antithrombin III were analysed and resulted in normal range such as inherited thrombophilia associated to Factor V Leiden and prothrombin A20210G gene polymorphisms." (PMID 16324213, 2005). "For instance, in a case report concerning a pregnant woman with RAO who was treated with aspirin was in fact diagnosed with familial thrombophilia and had elevated factor VIII and decreased protein S level." (PMID 39817651, 2025). "The thrombophilia assessment indicated that antithrombin III, protein C, protein S, factor VII, and factor VIII were within comparable ranges; anti-cardiolipin antibodies IgG and IgM were negative, and the JAK2 mutation was absent." (PMID 40095865, 2025). "Between 1 March 2020 and 28 February 2022, 567 potential living liver donors underwent thrombophilia testing that included anti-thrombin (AT) III, protein S (PS), anti-phospholipid antibody (APLA), and protein C (PC)." (PMID 38463105, 2024). "Inherited thrombophilia factors (Anti-thrombin III, Protein C, Protein S, and Factor V Leiden) were measured and the patients were followed for 3 months to evaluate the incidence of catheter-related thrombosis." (PMID 33815706, 2021). "However, considering the low level of protein-S activity, which decidedly induced the thrombus, and her own hypercoagulability, the marked decrease in fibrin catabolism could have led to the clinicians’ strong suspicion of thrombophilia." (PMID 30412129, 2018).
thrombophilia (continued). "Throughout pregnancy, a state of hypercoagulability is maintained, as reflected by the increased coagulation factors (I, II, VII, VIII, IX, XII, and von Willebrand factor), reduced protein S, and inhibition of fibrinolysis." (PMID 29907123, 2018). "However, we could not find this difference in other inherited thrombophilia’s including prothrombin mutation, hyperhomocysteinemia, protein S and C deficiency, AT-III deficiency, and PAI-1 mutation." (PMID 25114668, 2014). "Thrombophilia tests were normal, that is, testing for antithrombin III, protein C, protein S, lupus anticoagulant-1, while the molecular testing for FV Leiden, prothrombin gene, and MTHFR were negative too." (PMID 24151508, 2013). "This study was carried out to study the prevalence of seven common thrombophilia markers including LA, aCL, APC-R, AT, protein C, protein S and fibrinogen in an Asian Indian population with venous thrombosis, compared with controls without venous thrombosis." (PMID 21181065, 2010). "It is also important to note that TNF-α blockers block the escape of autoimmune B-cells, causing further upregulation of anticardiolipin antibodies, which inhibits the anticoagulant effects of protein C, protein S, and antithrombin III produced downstream of them and promotes hypercoagulability." (PMID 40351429, 2025). "We recommend that discontinuation of routine anti-phospholipid antibodies panel is reasonable, especially if other hereditary thrombophilia tests including protein C and protein S are negative." (PMID 38463105, 2024). "There were only 2 neonates with negative results, who were screened for thrombophilia mutations (F V Leiden, MTHFR, prothrombin G20210A, antithrombin III, protein C, protein S and plasminogen activator inhibitor)." (PMID 37271816, 2023). "Another physiological adaptation during pregnancy and the peripartum period is a hypercoagulable state, which leads to increased levels of thrombotic factors such as VII, VIII, X, XII, von Willebrand factor, and fibrinogen and reduced levels of protein S and fibrinolysis." (PMID 37046556, 2023). "Thrombophilia factors (protein S and protein C) were detected in 12 patients, and no protein C or S abnormality was found." (PMID 26090493, 2015). "All patients were tested for protein C and protein S activity to rule out congenital thrombophilia." (PMID 37753194, 2023). "In our case, some factors including antithrombin, protein C activity, protein S activity, and anticardiolipin antibodies (ACA) had been tested after thrombectomy, and no signs of thrombophilia were found." (PMID 26091450, 2015).
thrombosis (103 papers, 2004 to 2026). "Although protein S deficiency is classically associated with venous thrombosis, it has increasingly been implicated in arterial events." (PMID 40799883, 2025). "Certain chemotherapeutic drugs can cause deficiencies in protein C, protein S, and antithrombin, increasing the risk of blood clots (deep vein thrombosis or DVT)." (PMID 40520687, 2025). "The same variant was also detected in his son who suffered from deep vein thrombosis and decreased protein S activity as well." (PMID 36580209, 2023). "This description set into motion the research for other genetic causes for venous thrombosis, with subsequent reports of deficiencies of protein C in 1981, and protein S in 1984." (PMID 35860682, 2022). "In conclusion, it is equally important to consider protein S deficiency as a rare but important cause of deep vein thrombosis." (PMID 36705157, 2022). "Taken together, the p.R515C mutation of PROS1 is responsible for venous thrombosis episodes in the family." (PMID 34967380, 2021). "In contrast, Pros1 was identified as an anti-coagulating factor, as individuals with Pros1 deficiency suffer from severe recurrent venous thrombosis." (PMID 34771611, 2021). "PROS1 mutations are associated with an increased risk of venous thrombosis, and some reports suggest that PROS1 variants increase the risk of arterial embolism, such as cerebral infarction and myocardial infarction." (PMID 34496879, 2021). "The main clinical manifestations of most patients with heterozygous mutations in the protein S gene (PROS1) are lower extremity deep venous thrombosis and pulmonary embolism." (PMID 34496879, 2021). "Three patients had a previous history of deep vein thrombosis and one of these had protein S deficiency." (PMID 34501472, 2021). "The aim of the study was to evaluate the effects of HIV infection on the serum levels of C4b-binding protein (C4BP) and protein S as markers of predisposition to thrombosis in HIV-infected adults." (PMID 34522427, 2021). "For example, in a population of stroke patients, IL6 was upregulated, and it caused downregulation of Protein S that resulted in venous thrombosis." (PMID 32826388, 2020). "Deficiencies in antithrombin, protein C, protein S, factor V Leiden, and prothrombin gene in the homozygous state hold greater risk for venous thrombosis, but these mutations are considerably rarer." (PMID 31484330, 2019). "Two cases and literature review] [Unusual venous thrombosis revealing a human immunodeficiency virus infection and a protein S deficiency." (PMID 31447982, 2018). "Hereditary Protein S (PS) deficiency is a rare coagulation disorder associated with an increased risk of venous thrombosis (VT)." (PMID 28374852, 2017). "In our patient, as family screening was positive and despite the normal platelet count, patient had progression of thrombosis, and protein S has certainly increased the thrombotic risk of JAK2V617F positive MPN itself." (PMID 25878908, 2015). "In conclusion, protein S mutation appeared to be the primary cause of thrombosis in the family of the present study." (PMID 25997409, 2015). "Deficiencies of protein S, protein C, and antithrombin are rare and each of them is found in about 3% of patients with thrombosis." (PMID 25317347, 2014). "Cardiac thrombosis is a relatively rare condition in clinical practice, but the frequent presence of a prothrombotic defect, especially in antithrombin, protein C or protein S deficiency, in these patients indicates the need for a prothrombotic screening." (PMID 28352430, 2013). "In a study of 173 patients with deep vein thrombosis, 55 (32%) were found to carry mutations in genes encoding protein S, protein C, and antithrombin." (PMID 24250338, 2013). "Protein S is a vitamin K-dependent plasma anticoagulant protein and its deficiency leads to hypercoagulability syndromes with increased risk for venous thrombosis." (PMID 20637106, 2010).